CD36 (CD36 molecule (CD36 blood group))
Diseases named in the same sentence as CD36 in open-access papers (continued):
Sharing a sentence is not in itself a finding about the gene and the disease.
Obesity (continued). "Interestingly, CD36 mRNA and protein expression in adipose tissue was negatively correlated with intrahepatic TAG content presented as a marker of the metabolic disorders associated with obesity." (PMID 32796572, 2020). "CD36, one of the fatty acid transporters, was significantly upregulated in fish in the overfed group and is involved in facilitating cellular long-chain fatty acid uptake, inflammatory response, intestinal fat absorption, lipid storage in adipose tissue, and metabolic disorders, such as obesity." (PMID 32854279, 2020). "Therefore, the findings from this study support the idea that targeting both FASN and CD36 in combination may have therapeutic potential not only in cancer but also in metabolic disorders such as obesity and diabetes." (PMID 32850342, 2020). "Indeed, CD36 knockout mice are resistant to obesity and dysmetabolic disorders." (PMID 29270130, 2017). "The aim of this study was to compare FAT/CD36 regulation between primary human satellite cells isolated from healthy subjects and from obese type 2 diabetic patients in order to uncover new mechanisms of FAT/CD36 regulation associated with obesity and/or type 2 diabetes." (PMID 22194967, 2011). "Our recent study revealed that VAT from obese mice inhibits endothelial Kir2.1 function in a CD36-dependent manner, suggesting the VAT/CD36/Kir2.1 axis is a potential contributor to obesity-induced endothelial dysfunction." (PMID 40996861, 2025). "Proteins involved in lipid metabolism including ABCA1, CD36, and PLIN2 were reported to be specifically up-regulated in metabolically active macrophages in obesity." (PMID 40244655, 2025). "In obesity and T2DM, CD36 becomes constitutively localized at the membrane through S-acylation by zinc finger DHHC-type palmitoyltransferase 4 (zDHHC4), which is upregulated by forkhead box protein O1 (FoxO1) signaling." (PMID 41002965, 2025). "In obesity-related SAP, CD36 likely induces tissue inflammation by promoting ferroptosis in macrophages within epididymal adipose tissue." (PMID 40331957, 2025). "Animal models induced by obesity and a high-fat diet (HFD) also demonstrate an elevation in CD36 levels in hepatic steatosis." (PMID 39774047, 2025). "Recent studies have explored the effects of high-fat diets on gene expression in adipose tissue, revealing specific gene alterations that contribute to obesity and insulin resistance such as ADIPOQ, CD36, PPARG, and IL6." (PMID 40408066, 2025). "Nevertheless, the precise molecular mechanisms governing CD36-mediated regulation of ferroptosis and inflammatory responses across pancreas, epididymal adipose, and ATM compartments in obesity-related SAP have yet to be fully elucidated." (PMID 40331957, 2025). "To date, 4 key lipid metabolism regulators have been extensively investigated in obesity research: PPAR, CD36, serine active site-containing 1 (SERAC1), and adiponectin (ADPN)." (PMID 41345744, 2025). "The genetic variants of the CD36 gene, reducing CD36 transcript, could explain the differences in fat perception and fat preferences; on the other hand, the relationship between overweight/obesity and SNPs in CD36 among pregnant women has not been fully clarified." (PMID 38612648, 2024). "As obesity is strongly associated with increased circulating free fatty acids, we, therefore, hypothesized that VAT from obese mice induces a local upregulation of endothelial CD36, the major endothelial fatty acid translocase, that results in the inhibition of Kir2.1." (PMID 38586877, 2024). "In addition, OEA can modulate an increase in the expression level of fatty acid translocase CD36, subsequently regulating feeding behavior and inducing a sense of satiety, thereby having the potential to emerge as a promising therapeutic approach for anti-obesity and hypolipidemic treatments." (PMID 39728469, 2024).
Obesity (continued). "These genes are normally expressing at very low levels in the hepatocytes, but CD36 expression increases in NASH patients and VLDLR increases in some pathological conditions, such as obesity, diabetes, and NAFLD." (PMID 36830921, 2023). "Piperine decreases the mRNA levels of hepatic SREBP-1c, FAS, and CD36 but increases CPT1 expression and AMPK activation in HF diet-induced obesity." (PMID 37237919, 2023). "Collectively, this study suggests that the CD36 peptide, as a TSP1 antagonist, shows promise as a novel therapeutic approach for managing obesity-related metabolic disorders." (PMID 37980376, 2023). "Obesity occurs due to the abnormal regulation of adipogenesis, promoted by adipogenesis regulators such as PPARγ, C/EBPα, FAS, and CD36." (PMID 36838843, 2023). "The mechanism of action of vimentin was mediated by the expression of CD36 and the glucose transporter GLUT4 on the cell membrane of adipocytes, linking intermediate filaments and intracellular trafficking with obesity and insulin resistance." (PMID 37189422, 2023). "Enhanced LDL binding to CD36 and LOX-1 probably results from increased lipid oxidation in obesity, which is consistent with reduced antioxidant capacity of HDL observed in these patients." (PMID 37777014, 2023). "Specifically, VW extract suppressed obesity by downregulating PPAR-γ and its target genes (LPL, CD36, HMGCR, and L-FABP), thereby disrupting adipogenesis and lipid accumulation." (PMID 36193302, 2022). "A previous study demonstrated that upregulated MIR20B levels in obesity-induced metabolic disorders such as T2DM were considered to prevent several targets, such as STAT3, CD36, and PTEN, which are involved in glucose and lipid homeostasis." (PMID 34964438, 2021). "Taken together, CD36, COL4A2, GLUL, and ACACB were considered as core genes closely related to obesity and T2DM." (PMID 34085602, 2021). "CD36 modulates cellular FFA transfer, and studies with the Zucker diabetic fatty (ZDF) rat, an obesity-induced diabetic animal model, indicate that elevated levels of FFA cause ceramide accumulation, which destroys β-cells by apoptosis." (PMID 34206537, 2021). "Obesity induced by a high-fat diet (HFD) prior to tumor grafting resulted in increased tumor growth for WT and CD36 EC-KO littermates." (PMID 34314388, 2021). "Taken together, CD36, GLUL, COL4A2, and ACACB were considered as core genes in human adipose tissue with obesity or T2DM." (PMID 34085602, 2021). "-How do LPA and the CD36-PPAR-γ pathway regulate lipid accumulation and lysosome dysfunction in adipocytes and hepatocytes, in obesity?" (PMID 34957117, 2021). "SCD‐1 induces obesity by catalyzing the desaturation of SFA palmitate and stearate to MUFA palmitoleate and oleate (Li, Berk, McIntyre, & Feldstein, 2009), and FAS and CD36 also play a regulatory role in lipid metabolism (Jung, Cho, Ahn, Jeon, & Ha, 2013)." (PMID 32405382, 2020). "The expression of IL-10, CD36, TLR2, and HSP70 (stress and/or obesity-related genes) was significantly upregulated in overfed fish." (PMID 32854279, 2020). "In addition, some indications exist, that CD36 (fatty acid translocase) gene polymorphisms correlate to plasma lipid level variations, i.e., CD36 gene polymorphisms lead to OEA synthesis inability, thereby being more prone to developing metabolic syndrome including obesity." (PMID 30428553, 2018). "Additionally, the down-regulation of FABP4 and CD36 transcripts with LOCK suggests that changes in PRAT following LOCK may mirror changes observed in obesity given findings that obese men display a down-regulated adipose tissue fatty acid trafficking transcriptomic signature compared to lean men." (PMID 26678390, 2015). "These genes include CD36 (HDL-C), RPTOR (obesity) and ABCG5/ABCG8 (low-density lipoprotein cholesterol (LDL-C) and total cholesterol)." (PMID 26021296, 2015).
Obesity (continued). "Also, hepatic steatosis induced by HFD significantly increased CD36 expression, and forced expression of hepatic CD36 in lean mice was reported to increase hepatic fatty acid uptake and TG storage, further supporting the observation of hepatic exiting in diet-induced-obesity mice." (PMID 24224011, 2013). "SCD-1 and CD36 are involved in fatty acid uptake and oxidation, and mice that lack SCD-1 are lean and resistant to obesity." (PMID 23533476, 2013). "TLR/MyD88 is a classic signaling inflammatory response that also involves in obesity development and is inhibited by the overexpression of PPARγ via the negative control of the expression of TLR4, and then activates the expression of CD36 for promoting fatty acid uptake and fat accumulation." (PMID 40045630, 2025). "Therefore, the differential regulation of CD36 by tirzepatide across tissues provides strong evidence for its favorable targeting ability in the treatment of MASLD and obesity." (PMID 40837406, 2025). "Furthermore, in obesity-related SAP, CD36 promotes ferroptosis in pancreatic tissue, epididymal adipose tissue, and ATMs, thereby inducing inflammatory responses." (PMID 40331957, 2025). "While the expression of CD36 has not been extensively studied in the context of obesity and TNBC, elevated CD36 expression has been reported to promote cancer cell survival in HER2-positive breast cancer and to initiate metastasis formation." (PMID 39456610, 2024). "In contrast, we did not observe an effect of CD36 knockdown on Kir2.1 currents in cells that were not exposed to AT, suggesting a VAT-induced upregulation of CD36 that impairs Kir2.1 in obesity." (PMID 38586877, 2024). "Changes in the fatty acid receptor CD36, inflammatory receptor TLR4, and inflammatory nuclear transcription factor NF-κB p65 in PBMC subsets were used to further test the relationship between fatty acids and the inflammatory state in individuals with obesity." (PMID 37403139, 2023). "As expected, in the current study, CD36 peptide treatment did not affect obesity induced TSP1 expression in AT but antagonized TSP1’s functions and reduced macrophage accumulation and proinflammatory activation in AT, resulting in reduced AT inflammation." (PMID 37980376, 2023). "In addition, the high expression level of CD36 and LPL in N + samples further verified the importance of an exogenous supply of lipids in LNM, reflecting the impact of obesity on nodal metastasis in another way." (PMID 36397145, 2022). "In obesity, chronic membrane-localization of CD36 free fatty acid (FFA) translocase, but not other FFA transporters, enhances FFA uptake and intracellular lipid accumulation." (PMID 35954283, 2022). "While we did not observe any direct involvement of CD36 in our studies of obesity-induced breast cancer, both studies describe a critical role for fatty acid metabolism in cancer stemness." (PMID 35013251, 2022). "By comparison, lacteal junctions in Cd36ΔLEC mice although more discontinuous were not as fragmented as in Cd36−/− mice, so lymphatic lipid transport occurred but was defective resulting in lymph leakage with onset of inflammation and obesity." (PMID 34099721, 2021). "Remarkably, the reduced expression was found in particular for CRP and CD36 (respectively) genes in PGW of the DS group compared to the DIO rats, suggesting that seed supplementation can reduce the inflammatory status induced by obesity." (PMID 33807712, 2021). "In addition, loss of PCSK9 has also been shown to result in hepatic injury in mice with diet-induced obesity, an effect largely attributed to the effects of PCSK9 on its target CD36." (PMID 33643060, 2021). "We anticipate identifying the genes closely related to obesity and T2DM and further investigate their relationship with the CD36, COL4A2, GLUL, and ACACB as they may be target genes for future therapies." (PMID 34085602, 2021).
Obesity (continued). "↑CD68 marker in obesity and in T2DM.↓CD11b, CD11c, CD163 and CD169 in T2DM patients↑TNFα, iNOS, IL-6, CD16, CD36, and CD206 in the T2DM Metformin restored TNFα, iNOS, IL-6, CD11c, CD36, CD169 and CD206 in T2DM patients to levels equivalent to those of lean volunteers." (PMID 34163481, 2021). "Taken together, these findings show that in obesity, adipocytes and hepatocytes express higher levels of CD36, which leads to defective lysosome homeostasis and negatively regulates autophagic function." (PMID 34957117, 2021). "Intriguingly, LPA is critical in lipid metabolism in obesity, and it is possible to speculate that the hepatic PPAR-γ-CD36 pathway is regulated by LPA." (PMID 34957117, 2021). "SAT CD36 expression was upregulated in patients with obesity and T2DM, whereas in VAT it was not different in lean, overweight, and obese participant and was only increased in T2DM." (PMID 32796572, 2020). "Other potential obesity biomarkers were found among those proteins elevated in vesicles from lipid hypertrophied cells such as inter-alpha-trypsin inhibitor heavy chain H3 (ITIH3), Glut4, cathepsin B, osteopontin, CD36, or tissue factor." (PMID 32214011, 2020). "Previously, AC was shown to produce an anti-obesity and anti-inflammatory effect by maintaining intestinal integrity in DIO mice; moreover, CD36 deletion in endothelial cells of the small intestine resulted in impaired barrier function of the small intestinal in mice." (PMID 32164196, 2020). "Obesity increased gene expression of CD36 but did not affect CPT1, whereas these were both, with exercise training, an effect that was greater with HIIT compared with MICT." (PMID 32230849, 2020). "Moreover, a study correlating obesity and EMT in hepatocellular carcinoma (HCC) revealed that fatty acid uptake via fatty acid translocase (CD36) activates Wnt and TGFβ signaling pathways and intensifies HCC progression." (PMID 32793478, 2020). "Our results concerning monocyte CD36 and CD86 expression suggest an influence of obesity." (PMID 31936430, 2020). "A minor population of CD36+PD-1+ AT-SVF lymphocytes was further increased by western diet (p < 0.05), suggesting CD36 may regulate immune exhaustion during obesity and adipose inflammation." (PMID 31035848, 2019). "The AMPK pathway also includes CD36, an important regulator of cell adhesion and FA transport, and LEP gene, a major regulator of energy homeostasis, whose transcription, as expected, was up-regulated in obesity." (PMID 30838002, 2019). "Since both obesity and T2DM are pro-inflammatory states, we examined the expression of several M1 phenotype markers in PBMC of lean, obese, T2DM, and T2DM on Metformin, including CD86, CD11c, CD169, IL-6, TNFα, iNOS, and CD36." (PMID 30356719, 2018). "CD36 is a transmembrane protein of the class B scavenger receptor family, a broadly expressed membrane glycoprotein mediating the uptake of LCFA in adipocytes and fibroblasts, in arteriosclerosis, fatty liver, obesity and inflammatory responses, and so on." (PMID 26000608, 2015). "Quantitative real-time RT-PCR revealed that the level of CD36 mRNA in mice hearts was not significantly altered by HFD induced obesity." (PMID 26036798, 2015). "Similar to CD36, FATP expression is influenced by the microenvironment, especially in obesity." (PMID 25866768, 2015). "The explanation for why CD36 KO mice show reduced obesity despite having a similar food intake to WT mice is not known." (PMID 22615812, 2012). "Total macrophage content as measured by CD11b and the scavenger receptor (CD36) per gram of tissue was not increased in human obesity." (PMID 21298111, 2011). "The upregulation of CD36 by Celastrol might be responsible to restore the oro-sensory capacity to detect an LCFA in the mice that decreased fat taste perception in obese mice can be restored by chemical compounds that decrease obesity and inflammation." (PMID 40284173, 2025).
Obesity (continued). "Additionally, studies investigating monolaurate or CO showed reduced levels of CD36 in different tissues either alone or supplemented to an HFD (39%–45%kcal fat) as protective effects against fatty liver and obesity." (PMID 39619979, 2024). "This was achieved through improvements in metabolic parameters, including CD36/liver X receptor α (LXRα)/sterol regulatory element-binding protein 1c (SREBP1c), proprotein convertase subtilsin/kexin type 9 (PCSK-9), and HMGCR, ultimately ameliorating HFD-induced hypercholesterolemia and obesity." (PMID 39519447, 2024). "In addition, these studies in particular do not necessarily detail a role for VAT versus SAT in obesity-induced endothelial dysfunction; however, they further support a role for CD36 as a major player upstream of Kir2.1 impairment." (PMID 38586877, 2024). "Although, we could not detect any effect of AS160 silencing on CD36/SR-B2 mRNA expression, the influence of obesity was quite evident (∼55% of data variability)." (PMID 37602323, 2023). "Potentially, receptor-homing peptides could be used to deliver molecules neutralizing CD36 complex transport function and signaling specifically in WAT, hepatocytes, or other cells for the treatment of obesity, hepatosteatosis, type-2 diabetes, and metastatic disease." (PMID 35991116, 2022). "In addition, the activation of AHR/CD36 pathway promotes hepatic steatosis in mice, while inhibiting the activity of AHR and altering the expression levels of CYP1B1, PPARα, and SCD-1 that attenuate the diet-induced obesity and hepatic steatosis in mice." (PMID 34722615, 2021). "However, we believe that galectin 3 and LPA may also promote the expression of CD36 in NPC hepatocytes through the PPAR-γ pathway, contributing to lysosome dysfunction probably by analogous mechanisms observed in obesity." (PMID 34957117, 2021). "However, obesity did not make tumor growth dependency on CD36 more prominent compared with chow-fed mice." (PMID 34314388, 2021). "Of those changes identified in the tumor microenvironments of ccRCC subjects with obesity versus non-obese counterparts, those with the largest fold changes were CD36 (+2.514, P = 0.045), IDO1 (+2.46, P = 0.012), CFB (+2.0, P = 0.041), CD7 (-4.66, P = 0.046), and CCL21 (-5.28, P = 0.0097)." (PMID 32469992, 2020). "Phosphorylation, glycosylation, and palmitoylation of the extracellular site of CD36 can affect FA uptake rate as well, nevertheless whether the post-translational modification pattern of CD36 is affected by obesity and hyperlipidemia has not been studied yet." (PMID 30925738, 2019). "Collectively this suggests that changes in adipocyte biology, especially in the context of obesity, can alter CD36 expression in nonadipose cells such as cancer cells that may influence the inherent role that CD36 plays in cancer biology." (PMID 25866768, 2015). "We concluded that the serum sCD36 levels generally substituted for the severity of CD36 expression on the Kupffer cells in patients with CLD-C, and that serum sCD36 levels were dependent on obesity, but were neither associated with insulin resistance nor hepatic steatosis in those patients." (PMID 24016701, 2013). "The signals responsible for triggering inflammatory response in adipocytes during obesity, as well as the mechanism by which CD36 might promote this, are not yet understood." (PMID 22615812, 2012). "Importantly, this protective effect was independent of changes in body weight, suggesting that CD36 peptide, acting as an antagonist for TSP1, may offer a new therapeutic option for managing obesity-associated metabolic dysfunction." (PMID 37980376, 2023). "The observed lower expression of genes such as CD36 and FABP4 in melanoma may reduce the cellular internalization of fat and therefore make patients with melanoma less sensitive to a high dietary fat intake, explaining in part the obesity paradox observed in patients with melanoma." (PMID 32209538, 2020).